DKK1 (dickkopf Wnt signaling pathway inhibitor 1)
Diseases named in the same sentence as DKK1 in open-access papers (continued):
Sharing a sentence is not in itself a finding about the gene and the disease.
cancer (continued). "Our results indicate that DKK1 and SFRP1 may be potentially useful biomarkers for evaluating the beneficial effects of long-term exercise on physical fitness and metabolism as well as the prognosis of patients with cancer." (PMID 28178355, 2017). "Furthermore, we have yet to determine if DKK1 and SOST are similarly processed by cancer cells." (PMID 26545120, 2015). "The IHC study of DKK1 expression in 102 NSCLC specimens sections revealed that the positive expression of DKK1 is correlated with lymph nodes metastasis; it might be a predictor of cancer metastasis." (PMID 24391982, 2013). "To evaluate whether or not DKK-1 is produced by cancer tissues, we studied its expression on CaP and healthy tissues by RQ-PCR." (PMID 18978943, 2008). "It is too early to speculate as to whether DKK1 plays a role in cancer similar to its known function in normal cells and in embryogenesis." (PMID 17245340, 2007). "Thus, DKK1 blockade does not directly affect GR cancer cell growth." (PMID 40025612, 2025). "However, recent studies showed that DKK-1 might function through a non-classical Wnt signaling pathway, and the expression of DKK-1 may differ according to the cancer type." (PMID 34123800, 2021). "However, based on the present study showing that acute infections trigger overproduction of DKK1, elevated levels of DKK1 in the blood of patients with FA may reflect the presence of an inflammatory or stress response rather than cancer." (PMID 30028084, 2018). "Since it has been reported that DKK1 is a target for epigenetic inactivation by CpG island promoter hypermethylation in several forms of cancer, we hypothesized that epigenetic silencing could also be responsible for the lack of DKK1 in primary MM cells and cell lines." (PMID 22363428, 2012). "DKK1 is an antagonist of the canonical Wnt signaling pathway (β‐catenin‐dependent pathway), but recent reports found that high DKK1 expression may lead to the aberrant activation of Wnt signaling and could activate the noncanonical Wnt signaling pathway in cancers." (PMID 38525111, 2024). "Recent studies have shown that cancer stem cells (CSC) are relatively enriched in lung metastases due to their high invasive properties, and enriched CSCs can secrete negative Dickkopf1 (DKK1) feedback to inhibit their stem cell properties." (PMID 36467032, 2022). "More importantly, there was a negative correlation between levels of DKK1 and CD8+ T cells in the corresponding carcinomas, including HNSC, TGCT, CESC, and LUSC." (PMID 34093545, 2021). "For example, several genes such as DKK1/2, CSNK1A1, INPP5D, and INPPL1 in the cases we discussed in detail are not present on the cancer panels we examined, yet their functional roles in respective signaling pathways are well-documented." (PMID 27245685, 2016). "Human Dickkopf-1 (Dkk-1) upregulates a noncanonical Wnt/JNK pathway, resulting in osteoclast stimulation, cell proliferation, and epithelial-to-mesenchymal transition (EMT) of cancer cells." (PMID 34437475, 2021).
infection (18 papers, 2012 to 2026). The state of being infected such as from the introduction of a foreign agent such as serum, vaccine, antigenic substance or organism. "Together with the regulation of PMN/LPA aggregation which selectively draws host cells to the site of infection, DKK1 controls the developing milieu promoting susceptibility to infection." (PMID 40502169, 2025). "In that report, we found that DKK1 is maintained at a high concentration in L. major infected mice, and that depletion of platelets resulted in the complete loss of the DKK1 response to infection." (PMID 37885890, 2023). "Our results suggest that DKK1 signalling and Leishmania pathogen-associated molecular patterns appear to regulate the migration and sustenance of viable activated neutrophils in the infection site resulting in chronic type 2 cell-mediated inflammation." (PMID 39502693, 2024). "Thus, the continuity of platelet activation and DKK1 production observed at later phase of infection may be associated with TNF-alpha activated platelets." (PMID 37885890, 2023). "Activation of platelet TLR1/2 at the initiation of Leishmania major infection results in the release of the Wnt antagonist Dickkopf-1 (DKK1)." (PMID 41858624, 2026). "We have previously shown that DKK1 signaling via PMN-LRP6 increased neutrophil MPO expression in the infection site of L. major infected mice." (PMID 40502169, 2025). "Further, the percentage and number of neutrophils at the infection site of DKK1(PKO) and MyD88(PKO) infected mice were significantly reduced on day 3 PI." (PMID 40502169, 2025). "It is possible that the non-apoptotic neutrophils obtained from infected BALB/c mice include neutrophils that ingested Leishmania in the first hours post-infection and whose apoptosis was delayed initially by DKK1 released by the parasite-activated platelet." (PMID 39502693, 2024). "Given that DKK1 facilitates the infiltration of activated neutrophils to the infection site, we considered the possibility that platelet DKK1 induced by L. major infection blocks the apoptosis of the activated neutrophils." (PMID 39502693, 2024). "In conclusion, our study elucidates the role of DKK1 and parasitic components in regulating the infiltration and longevity of neutrophils at the infection site." (PMID 39502693, 2024). "Further inhibition of DKK1 activity resulted in a significant reduction in cells recruited to the site of infection." (PMID 37885890, 2023). "The DKK1 response was shown to be critical to the development of the Th2 response to infection through the induction of MAPK and mTOR signaling pathways." (PMID 37885890, 2023). "We showed previously that pre-treatment of mice with DKK1 inhibitor 24 hours prior to infection with L. major reduced the elevation of LPA formation at 4 h post-infection." (PMID 37885890, 2023). "Our study highlighted that DKK1 released by LPG-activated platelets regulates leukocyte platelet aggregation required for infiltration of leukocytes to the infection site." (PMID 37885890, 2023). "This is consistent with our earlier study that showed that inhibition of DKK1 diminished macrophage accumulation at the infection site, impaired Th2 polarization, and dampened parasitic load." (PMID 37885890, 2023). "Thus, this review integrates current evidence indicating that platelet-derived DKK1 functions as an early regulator of both innate and adaptive immune responses during Leishmania infection." (PMID 42311685, 2026). "Experimental findings from BALB/c mouse models indicate that Leishmania major infection promotes platelet activation and DKK1 release, leading to enhanced leukocyte-platelet aggregation and recruitment of neutrophils, macrophages, and dendritic cells to inflammatory sites." (PMID 42311685, 2026). "Furthermore, pre-treatment of mice with DKK1 inhibitor prior to infection with L. major reduced the elevation of leukocyte platelet aggregate formation found in blood of infected mice." (PMID 40502169, 2025).
infection (continued). "However, the infiltration of macrophages and dendritic cells to the infection site in DKK1(PKO) and MyD88(PKO) mice was significantly impaired on days 7 and 14 PI compared to infected BALB/c mice (& D)." (PMID 40502169, 2025). "The mechanism involved in the upregulation of LRP6 expression is unclear but may be the result of cytokines or other mediators produced in response to infection as well as DKK1 itself." (PMID 39502693, 2024). "This suggests that DKK1 signalling via its receptor (LRP6) might also regulate the migration of activated neutrophils to the infection site." (PMID 39502693, 2024). "In this study, we further explored the potential role of DKK1-LRP6 signalling in the migration and longevity of activated neutrophils in the infection site using BALB/c mice with PMNs deficient in LRP6 (LRP6NKO) or BALB/c mice deficient in both PMN LRP6 and platelet DKK1 (LRP6NKO DKK1PKO)." (PMID 39502693, 2024). "Further, inhibition of DKK1 in vivo or platelet depletion resulted in reduction in IL-4, IL-10 and L. major parasite burden as well as cellular recruitment to the draining lymph node and site of infection." (PMID 37885890, 2023). "Although TLR4 activation does not lead to DKK1 release from platelets,the finding that platelet TLR2 mediates the induction of DKK1 suggests that this mechanism may play a role in the initiation of infection and pathogenesis of other Leishmania species." (PMID 37885890, 2023). "Furthermore, repeated administration of DKK1 inhibitor led to significant reduction in cellular recruitment at the site of infection and to the draining lymph node." (PMID 37885890, 2023). "It is hypothesized that R. conorii suppresses DKK1 to prevent negative regulation of Wnt signaling, thereby keeping proinflammatory cytokine expression relatively low during infection." (PMID 31681283, 2019). "DKK1 levels in R. conorii-infected patient sera indicate a decline in secreted DKK1 throughout infection, but whether this is a direct result of pathogen manipulation has not been investigated." (PMID 31681283, 2019). "Further testing will be important to determine the actual mechanism leading to increased DKK1 production during infections and whether DKK1 is a marker of chronic or undetected infections secondary to other diseases such as FA." (PMID 30028084, 2018). "Interestingly, the levels of DKK-1 mRNA in the P1 infection group of lung and spleen significantly increased compared to those in the mock infected group, while decreased significantly in lymph nodes and livers." (PMID 29593670, 2018). "Thus, DKK1 prodution and platelet activation dissociate at the later phase of infection." (PMID 37885890, 2023). "Hence, as infection progresses the immune complexes formed could lead to sustained platelet activation and DKK1 release." (PMID 37885890, 2023). "Consistent with the decreased circulating LPA in DKK1(PKO) and MyD88(PKO) infected mice, data showed reduced NPA at the infection site of DKK1(PKO) and MyD88(PKO) infected mice on day 3 PI compared to BALB/c-infected mice." (PMID 40502169, 2025). "In this study, we have demonstrated that DKK1 produced via the TLR1/2-MyD88 dependent pathway elevates LPA and NPA formation, as well as the infiltration of activated neutrophils into the infection site of BALB/c-infected mice." (PMID 40502169, 2025). "Although the role of PMN recruitment and LPA formation clearly depends on DKK1, we considered the possibility that the deletion of MyD88 or the absence of DKK1 in platelets might also impact the infiltration of macrophages and dendritic cells to the infection site." (PMID 40502169, 2025). "At the site of infection, the levels of neutrophil platelet aggregates and activated neutrophils of MyD88(PKO) and DKK1(PKO) mice were reduced." (PMID 40502169, 2025).
infection (continued). "Thus, to characterize whether DKK1 promotes infiltration of activated neutrophils to the infection site, MHC class II and CD11b positive neutrophils obtained from the footpad of infected BALB/c, LRP6NKO, LRP6NKO DKK1PKO and non-infected BALB/c mice were assessed." (PMID 39502693, 2024). "In this study, we explored the role of DKK1 and LPR6 signalling in the migration and maintenance of viable activated neutrophils at the site of infection during the early development and establishment of disease (days 3 to 14)." (PMID 39502693, 2024). "Endogenous mmp2, mmp7, mmp9, DKK-1, c-myc and CCND-1 mRNA and β-catenin protein expression levels were detected in P1-infected ST cells at 24, 48, and 72 h post-infection and compared with those in uninfected cells." (PMID 29593670, 2018). "The capacity of R. conorii to down-regulate endothelial-derived DKK-1 and the ability of silencing DKK-1 to attenuate R. conorii-induced inflammation in endothelial cells could potentially reflect a novel mechanism by which R. conorii escapes the immune response at the site of infection." (PMID 23028464, 2012). "Also, our recent work has established that DKK1 signaling via its receptor (LRP6) elevates NPA formation and the migration of activated neutrophils to the infection site." (PMID 40502169, 2025). "Because DKK1 produced via the MyD88 activation signal promotes the migration of leukocytes to the infection site, we tested the hypothesis that the Th2 response in infected BALB/c mice may be mediated by DKK1 produced via a MyD88-dependent pathway." (PMID 40502169, 2025). "Since fewer MPO+, CD11b+, and MHC class II+ neutrophils were found in DKK1(PKO) and MyD88(PKO) infected mice, these data suggest that neutrophil persistent activation and migration to the infection site in BALB/c mice is promoted by DKK1 release via the MyD88 signaling pathway." (PMID 40502169, 2025). "Given the percentage of MPO-positive neutrophils in LRP6NKO and LRP6NKO DKK1PKO infected mice is decreased in comparison to BALB/c infected mice, these data further confirm that the interaction of DKK1 and LRP6 is essential for the migration of activated neutrophils to the infection site." (PMID 39502693, 2024). "The role of inflammatory cytokines (such as IL-6, IL-1 β, TNF - α) in inhibiting or regulating endogenous DKK1 expression has not been evaluated, and these factors may have an impact on local inflammation progression and fibrosis after AE infection." (PMID 40496021, 2025). "Also, the type of infection did not seem to influence DKK1 production, suggesting that no specific pattern‐recognition receptors critical for the host defence system are involved." (PMID 30028084, 2018). "Given that DKK1 is dysregulated in cells and mouse models of FA, that inflammation in FA leads to BMF and that DKK1 is activated in response to inflammation, we hypothesized that DKK1 levels increase in response to infections with or without accompanying inflammation." (PMID 30028084, 2018).
cardiovascular disease (12 papers, 2013 to 2023). "In this study, we primarily focused on the role of DKK1 in NAFLD development, and our findings are consistent with the previous findings where DKK1 was identified as a risk factor in cardiovascular disease." (PMID 36410795, 2023). "A significant increase in DKK-1 has also been found in patients with T2DM combined with cardiovascular disease, while a correlation between DKK-1 and vertebral fractures has not been demonstrated in these individuals." (PMID 37106471, 2023). "Clinical studies have established the importance of DKK1 in the development of cardiovascular disease, showing a correlation between its high serum levels and the risk of cardiovascular disease." (PMID 35203651, 2022). "Dickkopf-1 (DKK-1), a major regulator of the Wnt pathway, plays an important role in cardiovascular disease." (PMID 23359112, 2013). "Dickkopf-1 (DKK1) was recently shown to play an important role in cardiovascular disease." (PMID 33867842, 2021). "In recent years, DKK1 was also established as a novel mediator of cardiovascular disease." (PMID 33867842, 2021). "Targeting DKK1 therapies may not only have antitumor effects but also play protective roles in cardiovascular diseases, killing two birds with one stone." (PMID 33867842, 2021). "Therefore, revealing the role of DKK1 in the development of cardiovascular disease is important to guide the application of antitumor agents targeting DKK1 in tumors within the population of patients with cardiovascular disease." (PMID 33867842, 2021). "DKK1 concentrations according to the presence of cardiovascular disease in the T2DM group." (PMID 25369286, 2014). "DKK-1, as a major regulator of the Wnt pathway, plays a key role in cardiovascular disease." (PMID 23359112, 2013). "Both sclerostin and DKK1 may be considered mediators and markers of cardiovascular disease (CVD)." (PMID 28493902, 2017).
bone disorder (10 papers, 2016 to 2025). "DKK1 had been found to be associated with many skeletal diseases." (PMID 38744806, 2024). "Hetero-DS (Amgen), also known as AMG 147, is a bispecific antibody constructed on an IgG2 backbone, that targets sclerostin and DKK1 for the treatment of bone disorders, including fracture healing and bone formation." (PMID 40394415, 2025). "Additionally, compelling evidence supports the notion that the elevated expression of DKK-1 contributes to the development of erosive bone disorders, such as PsA." (PMID 37834418, 2023).
neurodegenerative disease (8 papers, 2013 to 2025). A disorder of the central nervous system characterized by gradual and progressive loss of neural tissue and neurologic function. "Therefore, it is easy to understand that Dkk1, a Wnt signaling inhibitor, is associated with the severity of neurodegenerative diseases." (PMID 33408628, 2020). "Indeed, while expression of DKK1 is required for proper neural development, overexpression of DKK1 is one characteristic of neurodegenerative diseases, including PD." (PMID 37691228, 2024). "Further, in vivo studies in rat and mouse and in vitro on neuronal cultures indicated that increased Dkk1 protein expression may contribute to cell death in cerebral ischemia, epilepsy, and neurodegenerative diseases." (PMID 33995117, 2021). "In addition, melatonin decreases some factors that are related to neurodegenerative diseases, such as amyloid β (Aβ) since Aβ accumulation induces Dkk1 production." (PMID 28507478, 2017). "Finally, the finding that Dkk1 is elevated in the AD brain has sparked enthusiasm that this molecule could be used as a biomarker at early stages of AD or other neurodegenerative diseases." (PMID 24223536, 2013). "The serum level of several bone-derived mediators has been found modulated in patient affected by bone diseases, as osteoporosis, but also in the case of neurodegenerative diseases, such as AD [e.g., OCN, OPN, sclerostin, Dkk-1, and lipocalin 2] and PD [e.g., bone morphogenic protein 2, OCN]." (PMID 33995117, 2021). "Unlike DKK1, Notum is an enzyme with a druggable pocket and antagonism of Notum activity may be of therapeutic value for the treatment of neurodegenerative diseases." (PMID 33033363, 2020). "Furthermore, except for OCN and DKK1, there is still a lack of direct evidence to show that these bone-secreted osteokines can cross the BBB and influence the neurodegenerative diseases’ course." (PMID 33408628, 2020).
adenocarcinoma (7 papers, 2015 to 2024). A common cancer characterized by the presence of malignant glandular cells. "In the adenocarcinoma population, the mentioned alterations in DKK1 were also linked to a significantly reduced overall survival, further supporting the importance of DKK1 in NSCLC." (PMID 26353782, 2015). "DKK1 is an antagonist of Wnt signaling, which is downregulated at the onset of adeno-carcinoma formation." (PMID 36868311, 2023). "The DKK1 RNAscope assay in conjunction with the digital image analysis solution is acceptable for prospective screening of G/GEJ adenocarcinoma patients." (PMID 33972574, 2021).
infectious disease (6 papers, 2018 to 2026). A disorder directly resulting from the presence and activity of a microbial, viral, or parasitic agent in humans. "Having established a genetic link between DKK1 and cytokine responses in healthy individuals, we next explored human DKK1 biology in the context of infectious disease." (PMID 36539532, 2022). "In our study, we did not observe any correlation between the number of platelets and DKK1 levels in blood from children with infectious diseases." (PMID 30028084, 2018). "By integrating current evidence on platelet-mediated immune regulation, this review highlights platelet-derived DKK1 as a potential immunomodulatory target and emphasizes the need for further studies to clarify its translational relevance across infectious diseases." (PMID 42311685, 2026).
gastrointestinal tumors (4 papers, 2008 to 2023). "There have been several studies on the DKK1/CKAP4 axis in gastrointestinal tumors." (PMID 37835450, 2023).